RN7SKP200 (RN7SK pseudogene 200)
Gene: Miscellaneous RNA gene on chromosome 2 (206,221,315 to 206,221,634, forward strand). Ensembl gene ENSG00000222496.
Homologues: Orthologues: chimpanzee 7SK (98% identical). Paralogues in human: RN7SKP180 (73% identical), RN7SKP47 (73% identical), 7SK (73% identical), RN7SKP176 (73% identical), RN7SKP162 (72% identical), RN7SKP189 (72% identical), RN7SKP203 (72% identical), RN7SKP217 (72% identical), RN7SKP243 (71% identical), RN7SKP90 (71% identical), RN7SKP170 (71% identical), RN7SKP255 (71% identical), and 284 more.